TCF4 (transcription factor 4)
Diseases named in the same sentence as TCF4 in open-access papers (continued):
Sharing a sentence is not in itself a finding about the gene and the disease.
schizophrenia (continued). "The analyses on the 28 individual SNPs previously associated with schizophrenia found that two SNPs in TCF4 returned a significant association with the SPEQ Paranoia dimension, rs17512836 (p-value = 2.57×10−4) and rs9960767 (p-value = 6.23×10−4)." (PMID 24718684, 2014). "Genome-wide association studies have also found that common variants in TCF4 are associated with an increased risk of schizophrenia." (PMID 24058414, 2013). "It is now well established that rare, highly penetrant TCF4 alleles are associated with neurodevelopmental phenotypes whereas common variants are associated with disorders such as schizophrenia." (PMID 24058414, 2013). "The rs9960767 polymorphism of the TCF4 gene was shown in a GWAS to increase the risk of schizophrenia only slightly." (PMID 24403877, 2013). "Genome-wide association studies found that a SNP (rs9960767) located in intron 3 of TCF4 was associated with schizophrenia (P = 4.1 x 10-9), surpassing the statistical threshold for genome-wide significance." (PMID 24058414, 2013). "Additional TCF4 variants have also been associated with schizophrenia providing further support for TCF4 as a schizophrenia risk gene." (PMID 24058414, 2013). "The TCF4 genotype did not affect intelligence or total verbal learning score, but decreased VDM performance in patients with schizophrenia who carried the C allele of the rs9960767 polymorphism of the TCF4 gene." (PMID 24403877, 2013). "It is noteworthy that according to the TCF4 gene structure described here, the SNP rs9960767 associated with susceptibility to schizophrenia is located in TCF4 intronic sequence between 5′ exons 5b and 5c." (PMID 21789225, 2011). "Specifically, human TCF4 gene is implicated in susceptibility to schizophrenia and TCF4 haploinsufficiency is the cause of the Pitt-Hopkins mental retardation syndrome." (PMID 21789225, 2011). "Transcription factor 4 (TCF4), a member of the basic helix–loop–helix family (bHLH) of proteins, has been causally linked to intellectual disability and neuropsychiatric diseases such as schizophrenia, major depression, or autism spectrum disorder." (PMID 40155049, 2025). "However, in 2020, a meta-analysis was conducted that confirmed the contribution of TCF4 rs2958182 to the predisposition to the development of schizophrenia." (PMID 41226544, 2025). "Thus, for the first time, we have discovered associations of the polymorphic variant TCF4 rs2958182 and TCF4 rs9636107 with the leading symptoms of schizophrenia in Caucasian patients of the Siberian region." (PMID 41226544, 2025). "Pathogenic variants in TCF4 leading to haploinsufficiencymay cause neurodevelopmental disorders, whereaspolymorphic variants localized in non-coding regions of thegene lead to its overexpression and appear to be associatedwith schizophrenia." (PMID 39722673, 2024). "TCF4 was associated with schizophrenia, intellectual disability and autism." (PMID 39135964, 2024). "In addition, single nucleotide polymorphisms within noncoding regions of the TCF4 locus lead to cognitive disruptions and are associated with schizophrenia." (PMID 39061390, 2024). "Additionally, PKA signaling induces transcription factor 4 (TCF4), a protein associated with cognitive deficits in schizophrenia, in cortical neurons." (PMID 38248228, 2023). "Moreover, impairment of Tcf4-expression in humans has been associated with psychiatric illnesses, such as schizophrenia and autism spectrum disorders." (PMID 37138023, 2023). "TCF4 is a transcription factor that has previously been associated with cognitive traits, educational attainment, alcohol consumption, autism spectrum disorder, schizophrenia, depression, lung function and BMI, as well as sleep duration." (PMID 37770476, 2023). "Transcription Factor 4 (TCF4) has been associated with autism and schizophrenia." (PMID 35501322, 2022). "TCF4 has also recently been shown to be a schizophrenia risk gene on its own." (PMID 34664540, 2022).
schizophrenia (continued). "TCF4 is implicated in schizophrenia and Pitt-Hopkins autism-like syndrome." (PMID 35440587, 2022). "Moreover, genome-wide association studies (GWAS) identified TCF4 polymorphisms linked with schizophrenia (SCZ) and other psychiatric conditions, as well as non-neurological genetic diseases." (PMID 33414364, 2021). "In addition, genetic variants in TCF4 have been linked to neuropsychiatric diseases, for example, schizophrenia and autism." (PMID 33462220, 2021). "Moreover, polymorphisms in TCF4 have been associated with schizophrenia and other psychiatric and neurological conditions." (PMID 33414364, 2021). "Inactivations, deletions and single nucleotide variations in human TCF4 have been associated with syndromic and non-syndromic forms of intellectual disability, schizophrenia, autism and several nervous system dysfunctions such as breathing abnormalities and seizures in Pitt-Hopkins syndrome." (PMID 32266943, 2020). "TCF4 gene has been strongly implicated in type II diabetes; however, recent data suggest that TCF4 is also an important regulator of neurodevelopment disorders such as schizophrenia, Fuchs’ endothelial corneal dystrophy, and primary sclerosing cholangitis." (PMID 33126517, 2020). "Moreover, SNPs in non-coding regions of the TCF4 gene are associated with an increased risk of schizophrenia and autism." (PMID 33228529, 2020). "In the original PGC2 study, TCF4 was GWAS-significantly associated with schizophrenia, and thus might have been driving the results." (PMID 31078131, 2019). "Although rs4309482 and rs12966547 of TCF4 appear to be risk factors influencing the phenotypes in schizophrenia, it seems unlikely that a SNP could account for a disorder as complex as schizophrenia." (PMID 31191620, 2019). "Increasing compelling evidence supports the crucial role of TCF4 during neurodevelopment and raises the possibility that TCF4 genetic perturbations may increase the risk for schizophrenia." (PMID 31191620, 2019). "The mechanisms underlying the effect of SNPs of TCF4 in schizophrenia deserve further exploration." (PMID 31191620, 2019). "In particular, TCF4 has been identified as a direct target of schizophrenia-associated pivotal factor miR-137, suggesting a particular susceptibility whereby TCF4 could be involved in the gene regulatory networks underlying schizophrenia." (PMID 31191620, 2019). "TCF4 is one of the most frequently reported schizophrenia risk genes." (PMID 29540662, 2018). "A total of 4168 genes were present in both the TCF4 target and schizophrenia risk loci datasets." (PMID 29228394, 2018). "In addition to schizophrenia, we found a significant enrichment for TCF4 targets associated with genes implicated in ASD and to a lesser extent ID." (PMID 29228394, 2018). "Of note, five (CNTN4, GATAD2A, GPM6A, MMP16, and TCF4) of the top six causal genes are involved in neurodevelopment, further supporting the neurodevelopmental hypothesis of schizophrenia." (PMID 29540662, 2018). "TCF4, which encodes a basic helix-turn-helix transcription factor, regulates gene expression in immune system and in brain development and is significantly associated with schizophrenia." (PMID 29321746, 2017). "Additional genetic evidence associates TCF4 with schizophrenia-relevant phenotypes." (PMID 27752241, 2016). "The largest genome-wide association study of schizophrenia to date shows further support for the role of immunological factors in the pathogenesis of symptoms: genes expressed in the immune cells, such as STAT6 and TCF4, were overrepresented in the genetic loci associated with schizophrenia." (PMID 25970596, 2015). "DNA sequence variation in ZNF804A and TCF4 has been robustly associated with schizophrenia risk." (PMID 25217366, 2014). "ZNF804A and TCF4 are believed to encode transcription factors, but little is known about the mechanistic pathways via which they might increase risk for schizophrenia." (PMID 25217366, 2014).
schizophrenia (continued). "Furthermore, in both samples, PPI was strongly decreased in carriers of the schizophrenia risk allele C of the TCF4 gene, whereas startle reactivity and habituation were unaffected by the TCF4 genotype." (PMID 24403877, 2013). "More informative genes including microRNA genes (e.g., miR-137 and TCF4) were recently reported to be associated with schizophrenia and could improve this approach." (PMID 23922650, 2013). "It is therefore possible that SNPs associated with schizophrenia may differentially regulate the expression of one or more TCF4 isoforms leading to subtle changes in critical neurodevelopmental pathways." (PMID 24058414, 2013). "In addition to rare mutations, common variants (single nucleotide polymorphisms, SNP) in TCF4 are associated with an increased risk of schizophrenia." (PMID 24058414, 2013). "The precise nature of the relationship between arginine and oxidative stress in neuropsychiatric disorders is unclear; however, the common susceptibility genes for ASD and schizophrenia, TCF4 and NOS1 has been suggested to be involved in the arginine-NO pathway." (PMID 24058493, 2013). "Notably, mutations in TCF4 cause Pitt–Hopkins syndrome, a neurodevelopmental disorder characterized by intellectual disability and developmental delay and have also been associated with schizophrenia and ASD." (PMID 39494521, 2024). "In addition, TCF4 targets have also been associated with schizophrenia." (PMID 39494521, 2024). "Thus the enhanced risk for schizophrenia associated with BHLHE22 could be related to the influence or interaction with TCF4, and its downstream targets." (PMID 34664540, 2022). "The CA10 and TCF4 genes exhibited a strong association with psychiatric traits, specifically “morningness” (P = 5.42 × 10−11 for CA10) and schizophrenia (P = 3.64 × 10−20 for TCF4)." (PMID 40291381, 2025). "Transcription factor 4 (TCF4) factor, also known as TCF7L2, is linked to the genetic risk of schizophrenia and plays a role in neuronal development as well as the regulation of gene expression in response to Wnt signaling and neural development." (PMID 41169352, 2025). "Torshizi A.D., Armoskus C., Zhang H., Forrest M.P., Zhang S.,Souaiaia T., Evgrafov O.V., Knowles J.A., Duan J., Wang K. Deconvolutionof transcriptional networks identifies TCF4 as a masterregulatorin schizophrenia." (PMID 39722673, 2024). "Transcription factor 4 (TCF4) has been implicated in a range of neuropsychiatric disorders, including major depressive disorder, bipolar disorder, and schizophrenia." (PMID 39502395, 2024). "By integrating the results from different prediction approaches, they identified six top candidates that represent promising causal genes for schizophrenia (CNTN4, GATAD2A, GPM6A, MMP16, PSMA4, and TCF4), including the GPM6A gene." (PMID 35328011, 2022). "Transcription factor TCF4 has been extensively studied due to its linkage with neurocognitive disorders such as intellectual disability, schizophrenia and Pitt-Hopkins syndrome." (PMID 36407762, 2022). "Consistent with our results, TCF4 transcript levels have been shown to be moderately increased in schizophrenia brains, suggesting long term upregulation of TCF4 expression." (PMID 36449485, 2022). "Schizophrenia-associated genes identified from snRNA-seq in postmortem brains were found to be highly regulated by a few TFs (SATB2, SOX5, MEF2C, and TCF4), also overlapping GWAS risk loci." (PMID 34299232, 2021). "Transcription factor 4 (TCF4), a master transcriptional regulator of schizophrenia risk genes and the genes involved in neural development and activity, is one of the schizophrenia susceptibility genes identified by GWASs." (PMID 34356078, 2021). "We conclude that environmental stress and Tcf4 misexpression precipitate cognitive deficits in 2-hit mouse models of relevance for schizophrenia." (PMID 33037178, 2020).
schizophrenia (continued). "Transcription factor 4 (TCF4) has been linked to human neurodevelopmental disorders such as intellectual disability, Pitt-Hopkins Syndrome (PTHS), autism, and schizophrenia." (PMID 33228529, 2020). "Given the strong associations of TCF4 and psychosocial stress with schizophrenia and MDD, it seems likely that relevant mechanisms are affected in our 2-hit Tcf4 gain- and loss-of-function mouse models." (PMID 33037178, 2020). "TCF4, a transcription factor involved in the development of the nervous system, is found to be a highly plausible candidate for contributing to schizophrenia." (PMID 31191620, 2019). "Using the PGC2 secondary analysis schizophrenia case-control cohort (N = 29,125 cases and 34,836 controls), a robust polygenic signal was observed from gene sets based on TCF4, FMR1, upregulation from MIR137 and downregulation from CHD8." (PMID 31078131, 2019). "This case-control study aimed to investigate the correlation of TCF4 rs13381800 and NRXN1 rs17039988 polymorphisms with the risk of schizophrenia in a sample of Iranian patients with schizophrenia." (PMID 32071599, 2019). "As a key regulator in the development of the central nervous system, transcription factor 4 (TCF4) has been shown to be involved in the pathogenesis of schizophrenia." (PMID 31191620, 2019). "The association between the polymorphisms of the TCF4 gene and NRXN1 gene with schizophrenia has been reported in many studies (19, 20, 21, 22, 23, and 24)." (PMID 32071599, 2019). "Other schizophrenia risk loci with TCF4 binding sites include DRD2, TSNARE1, and GRIA1, all of which are down-regulated in TCF4-depleted cells and MIR137/DPYD." (PMID 29228394, 2018). "Previous research has shown that smoking tobacco modulates the association between polymorphisms of transcription factor 4 and reduced sensory gating, an endophenotype of schizophrenia suggesting that the smoking of tobacco might play a role in early information processing deficits in schizophrenia." (PMID 30515111, 2018). "A third locus on chromosome 18 is located in a locus previously associated with schizophrenia, in the TCF4 gene (transcription factor 4; top PTSD SNP rs2123392, p = 5.4 × 10−11)." (PMID 30350223, 2018). "We found that GATAD2A and TCF4 were significantly upregulated in the hippocampus of schizophrenia cases compared with controls in GSE53987 dataset (P < 0.01)." (PMID 29540662, 2018). "It is known or predicted to regulate hundreds of genes, whose targets include many schizophrenia susceptibility genes, such as BDNF, ZNF804A, TCF4 and CACNA1C37,38." (PMID 29118371, 2017). "TCF4 mRNA expression is increased in human induced pluripotent stem cells (hiPSC) from schizophrenia patients and increased in postmortem DLPFC samples of miR-137 risk SNP carriers." (PMID 25941532, 2015). "It has occasionally been reported that the differences in risk-allele frequencies, such as genetic variation in the TCF4 gene and MHC region, for schizophrenia between East Asian and European populations." (PMID 25768306, 2015). "Here we studied the effects of schizophrenia risk genes MIR137, TCF4, and ZNF804A on macroscopic brain variation in healthy volunteers." (PMID 25217366, 2014). "In two accompanying papers, five schizophrenia susceptibility genes including CSMD1, C10orf26, CACNA1C, TCF4, and ZNF804A were validated as miR-137 targets, providing additional evidence for the involvement of miR-137 in schizophrenia." (PMID 25250332, 2014). "Mice with TCF-4 overexpression showed schizophrenia-related symptoms, and schizophrenia patients had reduced TCF-4 expression in the prefrontal cortex, which was negatively correlated with miR-137." (PMID 24566148, 2014). "Single nucleotide polymorphisms (SNPs) within the MIR137, TCF4, and ZNF804A genes show genome-wide association to schizophrenia." (PMID 25217366, 2014).
schizophrenia (continued). "TCF4 genotype sensorimotor gating modulation indicates a role for TCF4 gene variations in the development of early information-processing deficits in schizophrenia." (PMID 24403877, 2013). "The TCF4 SNP rs2958182 was found to interact with diagnosis of schizophrenia on IQ and attention-related task performance in a Chinese Han population." (PMID 24403877, 2013). "TCF4, like other MHC class I molecule alleles (VRK2 and ZNF804A), were found in genome-wide association studies (GWAS) to be associated with schizophrenia in an Irish population." (PMID 24403877, 2013). "To date, GWASs on schizophrenia have identified several genome-wide significant associated variants located in the zinc finger protein 804A (ZNF804A), neurogranin (NRGN), transcription factor 4 (TCF4) genes and a major histocompatibility complex (MHC) region." (PMID 24160291, 2013). "Understanding the roles of Da in the nervous system is important because its human ortholog, E-protein TCF4, is implicated in various nervous system disorders—mutations in TCF4 lead to an autism spectrum disorder Pitt–Hopkins syndrome (PTHS), and its common gene variants are linked to schizophrenia." (PMID 41500834, 2026). "In other ethnic populations, the association of polymorphic variants of the TCF4 gene with schizophrenia has not been studied." (PMID 41226544, 2025). "We hypothesized that the genes regulated by TCF4 in hMGEOs could provide functional insight into the role of TCF4 in neurodevelopmental disorders including schizophrenia." (PMID 35965434, 2022). "Notably, others have confirmed associations between miR-137 target genes CUB, CSMD1, C10orf26, CACNA1C, TCF4, and ZNF804A, and risk of schizophrenia." (PMID 34220567, 2021). "In the present case-control study, we evaluated the potential association of the four SNPs (rs9960767 rs2958182, rs4309482, rs12966547) of the TCF4 gene with schizophrenia in a sample of 1137 unrelated patients with schizophrenia and 1035 unrelated healthy people." (PMID 31191620, 2019). "One of the candidate genes in schizophrenia is transcription factor 4 (TCF4), which is positioned on chromosome 18 and is a transcription factor that plays a role in the transcription of Neurexin 1(NRXN1) gene, which is one of the candidate genes for developing schizophrenia." (PMID 32071599, 2019). "There is consistent evidence for the role of TCF4 in schizophrenia." (PMID 31078131, 2019). "All three signaling cascades (TCF4, CREB, WNT) have in common that they have been identified to mediate the risk for schizophrenia in humans, thus highlighting a possible role in the maintenance of synaptic function independently of their developmental functions." (PMID 29933371, 2018). "Importantly, we found that genes harboring de novo mutations in schizophrenia (P = 5.3 × 10−7), ASD (P = 2.5 × 10−4), and ID (P = 7.6 × 10−3) were also enriched among TCF4 targets." (PMID 29228394, 2018). "These lines of evidence suggest that TCF4 may have a crucial role in schizophrenia pathogenesis by modulating neurodevelopment." (PMID 29540662, 2018). "Haploinsufficiency of the class I bHLH transcription factor TCF4 causes Pitt-Hopkins syndrome (PTHS), a severe neurodevelopmental disorder, while common variants in the TCF4 gene have been identified as susceptibility factors for schizophrenia." (PMID 29588831, 2018). "These included replicated risk variants for schizophrenia associated with imaging phenotypes before, for example, rs11696094 (ZNF804A; ToM, RP), rs2007044 (CACNA1C; EM, RP), rs1702294 (miR137; EM) and rs9636107 (TCF4; EM)." (PMID 28072415, 2017). "TCF4 expression also differs in postmortem brains and blood from schizophrenia patients." (PMID 27752241, 2016).